MIR182 (microRNA 182)
Synonyms: hsa-mir-182; miR-182; MIRN182; miRNA182
Gene: MicroRNA gene on chromosome 7 (129,770,383 to 129,770,492, reverse strand). Ensembl gene ENSG00000207990.
Gene Ontology:
Biological process: miRNA-mediated post-transcriptional gene silencing
Diseases named in the same sentence as MIR182 in open-access papers:
MIR182 is named in the same sentence as 8 diseases in open-access papers, as found by Europe PMC text mining. Sharing a sentence is not in itself a finding about the gene and the disease. The quoted sentences say what the papers report.
glioma (1 paper, 2013). A benign or malignant brain and spinal cord tumor that arises from glial cells (astrocytes, oligodendrocytes, ependymal cells). "MIR135B, MIR182 and MIR183 are overexpressed in a wide range of other cancer types such as bladder, colon, prostate cancer and glioma." (PMID 24053169, 2013).
hearing loss (1 paper, 2018). "Germline mutations in Mir96, one of three co-expressed polycistronic miRNA genes (Mir96, Mir182, Mir183), cause hereditary hearing loss in humans and mice." (PMID 29476110, 2018).
cancer (3 papers, 2013 to 2025). A tumor composed of atypical neoplastic, often pleomorphic cells that invade other tissues. "MIR182 has been reported in literature in association with cancers and ocular diseases through model organisms as mouse (MGI database)." (PMID 40201796, 2025).
tumours (1 paper, 2024). "We identified MIR182, MIR183, MIR371, MIR373, MIR512-1, MIR512-2, MIR515-1, and MIR520e exhibiting high expression and MIR216b, MIR887, MIR9-2, and MIR9-3 exhibiting low expression in NANOG H/L tumours." (PMID 38693576, 2024).
MIR182 also shares sentences with these, for which no sentence is quoted: neuroblastoma (1 paper); pancreatic adenocarcinoma (1); periodontitis (1); prostate carcinoma (1).